UCHL1 (ubiquitin C-terminal hydrolase L1)
Diseases named in the same sentence as UCHL1 in open-access papers (continued):
Sharing a sentence is not in itself a finding about the gene and the disease.
glioma (8 papers, 2014 to 2026). A benign or malignant brain and spinal cord tumor that arises from glial cells (astrocytes, oligodendrocytes, ependymal cells). "Silencing UCHL1 in patient-derived glioma cells is associated with decreased GSCs self-renewal, proliferation, and invasion." (PMID 31387280, 2019). "Our loss of function studies using these pediatric high-grade gliomas cell lines showed that UCHL1 promoted cell growth, invasiveness, and self-renewal characteristics in vitro." (PMID 28472177, 2017). "UCHL1 promotes lymphatic metastasis, distant metastasis, and worse prognosis in glioma patients by enhancing GAS2 expression." (PMID 41425852, 2025). "KLC1 and TOP2A showed high levels of expression in almost every tumor type examined, while UCHL1 was found mainly in glioma." (PMID 36010968, 2022). "UCHL1 de-ubiquitinase is up-regulated in several cancers, including pediatric high-grade gliomas, where it contributes to promoting GSCs self-renewal, transformation, and invasion." (PMID 31387280, 2019). "Of note, AQ4 was the second most downregulated gene in the UCHL1 KDs (~37-fold reduction compared to controls), thus consistent with a possible function of UCHL1 in glioma CSCs." (PMID 28472177, 2017). "Using cell lines as model system we confirmed that UCHL1 was highly expressed in high-grade pediatric glioma SF188 and SJ-GBM2 cells compared to low-grade Res186 cells." (PMID 28472177, 2017). "Close to 50% reduction in clonogenicity was observed in the SF188 and SJ-GBM2 UCHL1 KDs, suggesting a functional role of UCHL1 in glioma malignant transformation." (PMID 28472177, 2017). "UCHL1 depletion in SF188 and SJ-GBM2 glioma cells was associated with decreased cell proliferation and invasion, along with a reduced ability to grow in soft agar and to form spheres (i.e. self-renewal measure)." (PMID 28472177, 2017). "To explore the relevance of UCHL1 in glioma growth and invasion, we carried out several in vitro analyses using a loss of function strategy." (PMID 28472177, 2017). "In this study, we knocked down the expression of UCHL1 in SF188 and SJ-GBM2 cell lines using a lentivirus transduction system of two different UCHL1 shRNA vectors, providing us a model system to elucidate the potential function of UCHL1 in glioma malignancy." (PMID 28472177, 2017). "A decrease on cell proliferation and in cellular invasiveness, together with an impaired sphere formation (in vitro surrogate assay for self-renewal), was observed in the knockdowns, which suggested a potential role for UCHL1 in high-grade glioma CSC function." (PMID 28472177, 2017). "In this work we used SF188 and SJ-GBM2 cell lines to study the function of the ubiquitin carboxyl-terminal esterase L1 (UCHL1), a deubiquitinase de-regulated in several cancers, in pediatric high-grade gliomas." (PMID 28472177, 2017). "In summary, our data indicated that UCHL1 might be an important factor in pediatric high-grade glioma progression, by sustaining the cancer stem cell population." (PMID 28472177, 2017). "UCHL1 might act as an oncogene in glioma within the gene network that imparts stem-like characteristics to these cancer cells." (PMID 28472177, 2017). "Nevertheless, the precise mechanisms driving UCHL1 de-regulation in glioma cells and whether the UCHL1 aberrant expression can influence the progression from low to high-grade glioma remains unknown." (PMID 28472177, 2017). "Our data suggested that UCHL1 might affect glioma growth and invasiveness, these are known properties associated with stem-like cell populations." (PMID 28472177, 2017). "Thus our cell-based assays suggested a potential role of UCHL1 in glioma cell transformation and cell invasiveness." (PMID 28472177, 2017). "Thus, the tissue microarray and cell lines data suggested a possible role for UCHL1 in the higher grade glioma cancer cells." (PMID 28472177, 2017).
glioma (continued). "Aberrant expression of UCHL1 in pediatric high-grade gliomas may promote cell invasion, transformation, and self-renewal properties, at least in part, by modulating Wnt/Beta catenin activity." (PMID 28472177, 2017). "Although the clinical relevance of UCHL1 expression in glioma seems possible, whether UCHL1 overexpression contributes to the malignant transformation/phenotype in astrocytoma has not been ascertain, and the molecular mechanism underlying its action in this context is also unclear." (PMID 28472177, 2017).
lymph node metastasis (7 papers, 2012 to 2026). "Ultimately, this study suggested the molecular mechanism by which CHGA and UCHL1 mediate the invasive pathway in CRC cells associated with the pathological Stage III lymph node metastasis." (PMID 37246623, 2023). "We found highlight chromogranin A and UCHL1 are linked together, whose levels are influenced as a prognostic and predictive biomarker in CRC tumour tissues with lymph node metastasis (LNM) Stage III." (PMID 37246623, 2023). "We investigated CHGA and UCHL1 proteins correlate with lymph node metastasis (J Cell Mol Med." (PMID 41938501, 2026). "Aberrations in the ubiquitin system also have been reported to be associated with various diseases, including cancer, for example, with elevated expression of Cathepsin D and Ubiquitin C-terminal hydrolase-L1 in tumor cells, the incidence of lymph node metastasis in CRC also has increased." (PMID 32127012, 2020). "However, only UCHL1 methylation was significantly correlated with the tumor stage and lymph node metastasis." (PMID 26550574, 2015). "Our data showed that UCHL1 methylation was significantly correlated with the TNM stage (p = 0.026) and lymph node metastasis (p = 0.014)." (PMID 26550574, 2015). "Compared with early stage GC or GC without lymph node metastasis, UCHL1 was more frequently methylated in advanced stage GC." (PMID 26550574, 2015).
osteosarcoma (7 papers, 2018 to 2025). A usually aggressive malignant bone-forming mesenchymal neoplasm, predominantly affecting adolescents and young adults. "This is true also in osteosarcoma where a study performed on a subset of patients, has associated UCHL1 with a worse prognosis and increased metastasis." (PMID 38534381, 2024). "Results from in vivo tumor formation experiments in mice also demonstrate that knockout of the UCHL1 gene suppresses the growth of osteosarcoma in nude mice." (PMID 39062505, 2024). "Knockdown of the UCHL1 gene markedly inhibits the proliferation and invasion of osteosarcoma cells, and induces apoptosis in them." (PMID 39062505, 2024). "Subsequent investigation on osteosarcoma cell lines has confirmed that UCHL1 is related to tumor progression, migration, and metastasis, as well as to increased AKT activation." (PMID 38534381, 2024). "This makes UCHL1 an oncogene, and a viable therapeutic target in osteosarcoma." (PMID 38534381, 2024). "Importantly, the downregulation of UCHL1 leads to decreased levels of p-Akt and p-ERK, which may be a key mechanism by which UCHL1 exerts its oncogenic effect in osteosarcoma." (PMID 39062505, 2024).
triple-negative breast carcinoma (7 papers, 2020 to 2026). An invasive breast carcinoma which is negative for expression of estrogen receptor (ER), progesterone receptor (PR), and human epidermal growth factor receptor 2 (HER2). "UCHL1 might play a role in the malignant progression of triple-negative breast cancer by maintaining dryness and promoting cell invasion." (PMID 37359528, 2023).
Alpha-Synucleinopathy (6 papers, 2012 to 2026). "Lastly, we investigated Ubiquitin C-terminal hydrolase L1 (UCHL1), a protein involved in protein degradation, and observed its elevation in α-synucleinopathies such as PD and DLB, while no significant elevation was observed in the MCI and AD groups." (PMID 37686075, 2023).
Huntington disease (6 papers, 2011 to 2022). Huntington disease (HD) is a rare neurodegenerative disorder of the central nervous system characterized by unwanted choreatic movements, behavioral and psychiatric disturbances and dementia. "Besides, in the queue of downregulated overlapping genes, loss of the UCHL1 gene is enough for the early onset of CNS neuronal disintegration in PD, AD, and Huntington's disease (AD) patients." (PMID 35958988, 2022). "UCHL1 (Ubiquitin C-Terminal Hydrolase 1) is identified as a major causal gene involved in the early-onset of familial and sporadic PD and other neurodegenerative disorders like AD and Huntington’s disease." (PMID 33028204, 2020). "Mutations in the human UCHL1 gene have been associated with various neurodegenerative disorders like PD, recessive hereditary spastic paraplegia (SPG79), AD and Huntington’s disease." (PMID 33028204, 2020).
spinal muscular atrophy (6 papers, 2015 to 2025). A motor neuron disease that affect the muscles, and characterized by muscle weakness and atrophy resulting from progressive degeneration and irreversible loss of the anterior horn cells in the spinal cord (i.e., lower motor neurons) and the brain stem nuclei. "Increases in UCHL1 have been detected using proteomic analysis of skin fibroblast cultures from patients with spinal muscular atrophy (SMA), a lethal hereditary condition caused by mutations in the survival of motor neuron 1 (SMN) gene." (PMID 31721001, 2019). "In the mousemodel, it was observed that elevation of UCHL1 in fibroblasts was associatedwith spinal muscular atrophy (Hsu etal., 2010)." (PMID 29658965, 2018). "For instance, after denervation damage, UCHL1 levels tend to rise in response to spinal muscular atrophy in an attempt to restore ubiquitin homeostasis by preserving ubiquitin levels and avoiding uncontrolled degradation." (PMID 36085166, 2022). "In a mouse model of the lower motor neuronopathy spinal muscular atrophy, knockdown of UCHL1 also had a detrimental effect on all phenotypes, leading the authors to conclude that increases in UCHL1 represent a compensatory response to disrupted ubiquitin homeostasis." (PMID 39548852, 2025).
atherosclerosis (5 papers, 2017 to 2025). A disease characterized by the build-up of fatty material and calcium deposition in the arterial wall resulting in partial or complete occlusion of the arterial lumen. "The newly indentified UCHL1 deficiency blocks lipid accumulation by macrophages, suggesting a potential link between UCHL1 and atherosclerosis." (PMID 32801299, 2020). "CD36 undergoes ubiquitination and covalent attachment of both K48 and K63 polyubiquitin chains; CD36-ubiquitin cleavage by deubiquitinases such as UCHL1 or USP11 modulates foam cell formation and atherosclerosis-linked outcomes." (PMID 40563926, 2025). "Targeting CD36, UCHL1 or USP11 using small molecule inhibitors or reverse genetic strategies could provide new strategies to target both atherosclerosis and cancer." (PMID 40563926, 2025). "Hence, this study provides a possible mechanism that UCHL1 mediates pathologic processes of atherosclerosis, indicating UCHL1 may be a therapeutic target in atherosclerosis treatment." (PMID 32801299, 2020). "Our study concluded that UCHL1 deletion decreases foam cell formation by promoting the degradation of CD36 protein, indicating UCHL1 may be a potential target for atherosclerosis treatment." (PMID 32801299, 2020). "Another study also found that UCHL1 inhibits lipid accumulation and foam cell formation by promoting the degradation of CD36 protein, indicating that UCHL1 may be a potential target for atherosclerosis treatment." (PMID 39944823, 2025). "However, the correlation between atherosclerosis and UCHL1 expression is not clear." (PMID 32801299, 2020).
Constipation (5 papers, 2016 to 2025). Infrequent or difficult evacuation of feces. "The comparable intensity and distribution of Uchl1 IR in the bladders between the two groups indicate that constipation did not alter bladder innervation at appreciable level." (PMID 33441874, 2021).
delirium (5 papers, 2016 to 2026). A disorder characterized by confusion; inattentiveness; disorientation; illusions; hallucinations; agitation; and in some instances autonomic nervous system overactivity. "The biomarker UCHL1 has yet to be investigated in delirium and could provide a novel way to predict and screen patients at risk for delirium following cardiac surgery by directly detecting injury to neurons." (PMID 27119013, 2016). "Increased delta power emerges as the most prominent finding in qEEG analyses of delirium, showing significant positive correlations with UCHL-1 and Tau protein, which indicates that encephalopathy severity corresponds to the extent of neuronal injury and neuroinflammation." (PMID 41360904, 2025). "Our research adds evidence of elevated NFL and tTau levels in delirium, suggesting that they are more pertinent than GFAP and UCHL-1." (PMID 38566855, 2024). "In patients with delirium, we observed strong correlations between the SBT at three months and Tau protein at day 3 (r = 0.675, p = 0.016), E-Selectin at day 7 (r=-0.617, p = 0.043) and UCHL-1 at discharge (r = 0.936, p < 0.001)." (PMID 39352661, 2025). "A recent prospective study on postoperative delirium identified elevated NFL levels but not tTau, GFAP, or UCHL-1 levels." (PMID 38566855, 2024).
glioblastoma (5 papers, 2014 to 2022). The most malignant astrocytic tumor (WHO grade IV). "Collectively, these data show that inhibition of UCHL1 by GK13S in the glioblastoma cell line U-87 MG on a molecular level phenocopies a pathogenic UCHL1 mutation in mice." (PMID 36216817, 2022). "We reconstituted the effect in a human glioblastoma cell line through controlled small-molecule-mediated inhibition of endogenous UCHL1." (PMID 36216817, 2022). "Our in vitro functional studies and gene expression data demonstrated that UCHL1 regulates glioblastoma CSCs populations and suggested wnt as a potential pathway mediating UCHL1 activity." (PMID 28472177, 2017). "Phenocopying the effect that an inactivating mutation of UCHL1 has on the mouse brain, GK13S, but not GK16S, led to the reduction of monoubiquitin levels in the human glioblastoma cell line U-87 MG." (PMID 36216817, 2022). "Phenocopying a reported inactivating mutation of UCHL1 in mice, GK13S, but not GK16S, leads to reduced levels of monoubiquitin in a human glioblastoma cell line." (PMID 36216817, 2022).
heart failure (5 papers, 2014 to 2026). Inability of the heart to pump blood at an adequate rate to meet tissue metabolic requirements. "However, recent work with cardiomyocyte selective deficiency of PGP9.5/UCHL1 suggests a protective effect of the enzyme in a post‐MI heart failure model." (PMID 40365781, 2026). "Therefore, this study demonstrates for the first time that UCHL1 supports autophagic flux in cardiomyocytes and that UCHL1 upregulation in cardiomyocytes in response to cardiac stress promotes cardiac proteostasis and protects against post-MI maladaptive cardiac remodeling and heart failure." (PMID 35463782, 2022).
intracranial hemorrhage (5 papers, 2020 to 2025). Bleeding within the SKULL, including hemorrhages in the brain and the three membranes of MENINGES. "A recent study demonstrated that glial fibrillary acidic protein and ubiquitin c-terminal hydrolase L1 can be used in combination to safely both rule in and rule out intracranial hemorrhage and to some extent predict the need for neurological intervention." (PMID 31089789, 2021).
ischemia (5 papers, 2013 to 2025). A hypoperfusion of the BLOOD through an organ or tissue caused by a PATHOLOGIC CONSTRICTION or obstruction of its BLOOD VESSELS, or an absence of BLOOD CIRCULATION. "To study the role of UCHL1 in muscle injury and recovery, we developed a model of non-invasive hindlimb ischemia-reperfusion (IR) injury based on a previously published study." (PMID 39000437, 2024). "Indeed, brain injury following trauma or peri-traumatic ischemia increases the concentration of specific biomarkers, such as S100β protein, neuronal-specific enolase (NSE), ubiquitin C-terminal hydrolase-L1 (UCH-L1), and glial fibrillary acidic protein (GFAP)." (PMID 31547411, 2019).
lung fibrosis (5 papers, 2021 to 2025). "As smoking is closely associated with various airway diseases, in addition with pulmonary fibrosis, UCHL1 expression in epithelium might provide a molecular link between smoking and airway submucosal fibrosis." (PMID 38016026, 2023). "Genetic deletion/depletion of UCHL1 or chemical inhibition of UCHL1 DUB activity is sufficient to reduce levels of fibrotic markers in liver, cardiac and lung fibrosis, demonstrating a key role for UCHL1 in promoting fibrosis in multiple organs." (PMID 38808772, 2024). "Recent work using an alternative UCHL1 inhibitor, IMP-1710, revealed a reduction of expression of profibrogenic markers in fibroblasts isolated from patients with idiopathic pulmonary fibrosis, demonstrating the importance of UCHL1 signalling in fibrosis." (PMID 38808772, 2024). "Ubiquitin carboxy-terminal hydrolase L1 (UCHL1), a deubiquitinating enzyme (DUB), is a potential drug target in various cancers, and liver and lung fibrosis." (PMID 34820624, 2021).
membranous nephropathy (5 papers, 2013 to 2025). "Injured podocytes often exhibit overexpression of the deubiquitinating enzyme ubiquitin C-terminal hydrolase L1 (UCH-L1), causing impaired proteasomal degradation and exacerbating glomerular damage in conditions like membranous nephropathy and focal segmental glomerulosclerosis (FSGS)." (PMID 40149885, 2025). "The level of anti-UCHL1 antibody was elevated in serum of patients with FSGS (focal segmental glomerulosclerosis) compared with IgAN, membranoproliferative glomerulonephritis and membranous nephropathy, indicating that anti-UCHL1 antibody might be a biomarker for diagnosis of FSGS." (PMID 38175721, 2024).
Obesity (5 papers, 2017 to 2025). Accumulation of substantial excess body fat. "Among these GRNs, the cross-tissue GRN ALPLIN78 stood out and should serve as a future target to prevent obesity and type 2 diabetes possibly by targeting UCHL1 in fat." (PMID 39973987, 2025). "UCHL1, a ubiquitin carboxyl-terminal hydrolase isozyme L1, has been shown to be a fetal programming-related obesity marker and could reflect the metabolic response of the inflammation state." (PMID 31929791, 2019). "Lap18, Cnpy2, Hnrnpk and Uchl1 expression levels in the rat hippocampus might be related to obesity-induced memory impairments, but the reasons for the dysregulation of these genes were still not clear." (PMID 29937895, 2017). "In this study, IPA eased the identification of obesity markers, and we chose ASCL1, HADH, and UCHL1 for validation based on both our proteomic analysis and previous research." (PMID 31929791, 2019).
parathyroid carcinomas (5 papers, 2010 to 2023). "Some studies assessed the role of additional molecular marker to complement parafibromin staining in the screening process, emerging the protein 9.5 (PGP9.5) encoded by the ubiquitin carboxyl-terminal esterase L1 (UCHL1), that was found to be upregulated in the majority of parathyroid carcinomas." (PMID 22567348, 2011). "For example, protein gene product 9.5 (PGP9.5), encoded by the ubiquitin carboxyl-terminal esterase L1 (UCHL1) gene has been shown to be upregulated in the majority of parathyroid carcinomas based on gene expression profiling, and the results were verified by immunohistochemistry." (PMID 21197463, 2010).